TCF12 (transcription factor 12)
Diseases named in the same sentence as TCF12 in open-access papers (continued):
Sharing a sentence is not in itself a finding about the gene and the disease.
melanoma (9 papers, 2019 to 2025). A malignant, usually aggressive tumor composed of atypical, neoplastic melanocytes. "We found that the expression level of TCF12 is elevated as melanoma progresses, and high expression is strongly associated with poor survival outcomes in melanoma patients." (PMID 37760480, 2023). "Studies have shown that TCF12 promotes cancer metastasis in hepatocellular carcinoma, colorectal cancer, and melanoma." (PMID 40166462, 2025). "Together, we confirmed that TGFB2 was essential for TCF12 to induce melanoma proliferation, migration, and invasion." (PMID 37760480, 2023). "In this study, we explored the functional involvement and molecular mechanisms of TCF12 in melanoma." (PMID 37760480, 2023). "In summary, we identified that TCF12 can directly bind to the Tgfb2 promoter and activate its expression in melanoma." (PMID 37760480, 2023). "Collectively, these results indicate that TCF12 has an oncogenic function and promotes melanoma tumorigenesis both in vitro and in vivo." (PMID 37760480, 2023). "To examine the expression of TCF12 in melanoma patients, we utilized the GEPIA (Gene Expression Profiling Interactive Analysis) online platform to profile TCF12 mRNA levels in melanoma patients and normal tissues." (PMID 37760480, 2023). "To further validate the findings from the public dataset, we performed TCF12 immunohistochemistry (IHC) on a melanoma tissue array." (PMID 37760480, 2023). "In this paper, we report that TCF12 expression is higher in melanoma, especially in metastatic tumors, through analyzing data from TCGA." (PMID 37760480, 2023). "We further employed IHC on the matched mouse melanoma tissues to validate that TCF12 depletion decreased TGFB2 protein while TCF12 overexpression boosted TGFB2 levels." (PMID 37760480, 2023). "In this study, we explored the function of a novel transcriptional activator, TCF12, in melanoma progression." (PMID 37760480, 2023). "In line with the bioinformatic analyses, our results demonstrated that the TCF12 protein was upregulated in melanoma and elevated progressively as the tumor advanced." (PMID 37760480, 2023). "Subsequently, we carried out ectopic TCF12 expression experiments and found that TCF12 overexpression promoted melanoma cell proliferation and colony formation." (PMID 37760480, 2023). "In contrast, overexpression of TCF12 in melanoma enabled the cells to establish larger and larger tumor nodules in the lung upon tail-vein injection." (PMID 37760480, 2023). "Then, cell proliferation, colony formation, and transwell assays show that the upregulated expression of TCF12 can promote proliferation and metastasis of melanoma cells in vitro." (PMID 37760480, 2023). "Collectively, our study supported the oncogenic functions of TCF12 in melanoma, revealing it as a potential target to improve the efficacy of BRAF(V600E)-targeted therapy." (PMID 37760480, 2023). "Our study suggests that TCF12 is a new player in this intricate network of genetic interactions that contribute to melanoma progression." (PMID 37760480, 2023). "To explore the biological function of TCF12 in melanoma, we first generated stable TCF12 knockdown in both human and mouse melanoma cells (A375 and YUMM1.7)." (PMID 37760480, 2023). "The results revealed that melanoma tissues had a notably elevated expression of TCF12 compared to adjacent normal skins." (PMID 37760480, 2023). "Taken together, these findings indicate that TCF12 promotes melanoma metastasis in vitro and in vivo." (PMID 37760480, 2023). "We found that depletion of TCF12 substantially reduced melanoma proliferation in response to PLX4032, as measured by the cell growth curve and colony formation." (PMID 37760480, 2023). "In vitro transwell migration and Matrigel invasion assays showed that TCF12 knockdown reduced the migration and invasion of melanoma cells, whereas TCF12 overexpression greatly enhanced their migratory and invasive capacities." (PMID 37760480, 2023).
melanoma (continued). "Subsequently, we screened a set of melanoma-related target genes with TCF12 binding sites by RT-qPCR and verified that TCF12 knockdown significantly decreased Tgfb2 transcription, leading to reduced protein expression." (PMID 37760480, 2023). "To elucidate the key molecules involved in TCF12-induced proliferation and metastasis in melanoma, we performed RNA-seq analysis on YUMM1.7 cells with scramble control or TCF12 knockdown." (PMID 37760480, 2023). "Our finding that TGFB2 is a direct transcriptional target of TCF12 suggests a mechanism by which TCF12 contributes to melanoma progression." (PMID 37760480, 2023). "Our findings shed light on a novel aspect of melanoma pathogenesis, uncovering the oncogenic functions of TCF12 and its regulatory mechanism within the disease." (PMID 37760480, 2023). "The volcano plot showed that 372 and 109 genes were significantly downregulated and upregulated upon TCF12 depletion in melanoma cells, respectively." (PMID 37760480, 2023). "Functionally, TCF12 enhances melanoma proliferation and metastasis, as well as the sensitivity to BRAF(V600E)-targeted therapy." (PMID 37760480, 2023). "Overall, our results demonstrate that TCF12 promotes melanoma progression and can be a potential tumor therapeutic target." (PMID 37760480, 2023). "TCF12 enhances melanoma cell proliferation, metastasis, and sensitivity to BRAF(V600E)-targeted therapy." (PMID 37760480, 2023). "We found that TCF12 is upregulated in melanoma, and high expression is correlated with disease progression and a poorer prognosis." (PMID 37760480, 2023). "Functionally, we found that TCF12 can enhance melanoma proliferation and metastasis, as well as sensitivity to BRAF(V600E)-targeted therapy." (PMID 37760480, 2023). "However, the translation of these findings into clinical applications will require further investigations, including preclinical studies and potentially clinical trials, to validate the efficacy and safety of targeting TCF12 in the treatment of melanoma." (PMID 37760480, 2023). "Interestingly, depletion of TCF12 can sensitize melanoma to BRAF inhibition both in vitro and in vivo." (PMID 37760480, 2023). "Similarly, knockdown of TCF12 significantly compromised the metastatic outgrowth of melanoma cells in mice after tail-vein injection, as revealed by improved animal survival and fewer macroscopic and microscopic tumor nodules in the lung." (PMID 37760480, 2023). "Next, we tested whether TCF12 affected the tumorigenesis of melanoma in vivo in an immunocompetent background." (PMID 37760480, 2023). "Moreover, patients with an increased TCF12 expression level showed reduced overall survival, suggesting a role for TCF12 in melanoma progression." (PMID 37760480, 2023). "Moreover, TCF12 has been proved as an oncogene in different tumors, including pancreatic carcinoma, melanoma, and hepatocellular carcinoma." (PMID 36377508, 2023). "Particularly, the detection of ECM–receptor interaction, focal adhesion, cGMP, cAMP, and PI3K-AKT signaling pathways among the top lists for downregulated genes was consistent with our observation that knockdown of TCF12 impaired melanoma proliferation and metastasis." (PMID 37760480, 2023). "Indeed, we confirmed that the expression of TCF12 increases as disease progresses, as evidenced by higher levels in metastatic tissues than in primary melanomas." (PMID 37760480, 2023). "Given the critical functions of the TGF-β pathway in cancer biology, we speculated whether TGFB2 mediates the tumorigenic activity of TCF12 in melanoma." (PMID 37760480, 2023). "Furthermore, we found that TCF12 depletion sensitizes melanoma cells to BRAF inhibition, suggesting that TCF12 may represent a potential therapeutic target for enhancing the efficacy of current BRAF-targeted therapies." (PMID 37760480, 2023). "We continued to investigate whether TCF12 in melanoma affected cell migration and metastasis." (PMID 37760480, 2023).
melanoma (continued). "However, whether TCF12 regulates melanoma progression and, if yes, by what mechanism, remain elusive to date." (PMID 37760480, 2023). "Interestingly, our early studies suggested that TCF12 may be a functional partner of PGC1α, likely playing a role in melanoma metastasis." (PMID 37760480, 2023). "For example, the lncRNA MIAT binds to TCF12 and facilitates its binding to the promoter region of NFAT5 gene, thereby activating NFAT5 expression and promoting melanoma cell proliferation, migration, and invasion." (PMID 39768127, 2024). "Studies have demonstrated that TCF12 can regulate TGF-β2 and contribute to melanoma tumorigenesis." (PMID 40166462, 2025). "We then measured the TCF12 protein stability in melanoma cells with or without BRAF inhibition and found that suppression of the BRAF pathway greatly reduced TCF12 protein stability." (PMID 37760480, 2023). "We found that, despite the fact that depletion of TGFB2 on its own did not alter melanoma proliferation, it was able to block the growth advantage conferred by TCF12 overexpression." (PMID 37760480, 2023). "The overexpression of lncRNA-MIAT obviously promotes the proliferation, migration and invasion of melanoma cells by regulating the PI3K/AKT signaling pathway and can also strengthen the interaction between TCF12 and the NFAT5 promoter region to promote the progression of melanoma." (PMID 36601121, 2022). "Thus, AKT3, HDAC9, TCF12, and LEF1 were differentially expressed in the melanoma specimens, tracking with CD271 enrichment." (PMID 31118427, 2019). "Interestingly, we also found that even within the primary melanomas, the vertical growth phase (VGP) tumors, which have penetrated deeper into the skin layers, showed a higher level of TCF12 compared to tumors in the radial growth phase (RGP), which represent the very early stage of melanoma." (PMID 37760480, 2023).
hepatocellular carcinoma (7 papers, 2019 to 2024). A malignant tumor that arises from hepatocytes. "Previous study reported that TCF12 enhances cell proliferation, migration, and invasion of hepatocellular carcinoma by activating the PI3K/AKT signaling pathway." (PMID 38725030, 2024). "Somatic genetic alterations of TCF12 (i.e. overexpression in hepatocellular carcinoma, ovarian and colorectal cancer, or compromise activity in anaplastic oligodendroglioma, prostate cancer) enhance cell proliferation, migration, and invasion, are related to more aggressive cancer course." (PMID 39036055, 2024). "For example, TCF12 expedites hepatocellular carcinoma (HCC) by upregulating CXCR4 and its ligand CXCL12 and activating the MAPK/ERK and PI3K/AKT pathways." (PMID 33413401, 2021). "Transcription factor 12 (TCF12) could directly bind to the CXCR4 promoter to up-regulate the expression of CXCR4, thereby enhancing the proliferation, migration, and invasion of hepatocellular carcinoma cells." (PMID 37497001, 2023).
oligodendroglioma (7 papers, 2015 to 2025). A well-differentiated (WHO grade II), diffusely infiltrating neuroglial tumor, typically located in the cerebral hemispheres. "Conversely, loss-of-function of TCF12 resulted in increased necrosis, mitotic index, cell proliferation, migration, and invasion in prostate carcinoma and oligodendroglioma." (PMID 39036055, 2024). "TCF12 mutations occurred only among oligodendrogliomas 1p19q codeleted with TERT promoter mutations and with IDH1 or IDH2 mutations (particularly frequent among IDH2-mutated tumors)." (PMID 30279357, 2018). "A recent study reported the mutation of an oligodendrocyte-related transcription factor TCF12 in 7.5% of anaplastic oligodendrogliomas: the mutations compromise TCF12 transcriptional activity and are associated with an aggressive tumor phenotype." (PMID 30279357, 2018). "We evaluated TCF12 expression and subcellular localization for all of our 11 TCF12-mutated tumours (10 AO and 1 oligodendroglioma grade II) and 11 TCF12 wild-type tumours by immunohistochemistry." (PMID 26068201, 2015). "To gain further insight into the role of TCF12 mutation in oligodendroglioma, we sequenced 75 grade II tumours identifying one mutation carrier (P212fs*31)." (PMID 26068201, 2015). "A recent study identified the presence of TCF12 mutations in oligodendrogliomas that impair TCF12 transcriptional activity and associated with more aggressive tumor types, suggesting that these TCF12 mutations may have an important role in their development." (PMID 34603319, 2021). "Histologic analysis of the TCF12 KO tumors revealed an extracellular matrix that is very reminiscent of human oligodendroglioma." (PMID 37046694, 2023). "Another point is that we cannot denote our TCF12 KO tumors as oligodendrogliomas given the strict requirement for 1p19 co-deletion for oligodendrogliomas by the World Health Organization classification." (PMID 37046694, 2023).
Intellectual disability (6 papers, 2015 to 2024). "We report on the first case of TCF12 microdeletion, detected by array‐comparative genomic hybridization, in a 72‐year‐old patient presenting with intellectual deficiency and dysmorphism." (PMID 25871887, 2015). "We postulate that the TCF12 microdeletion is responsible for this patient's intellectual deficiency and facial phenotype." (PMID 25871887, 2015). "We postulate that TCF12 microdeletion is responsible for the intellectual deficiency observed in our patient." (PMID 25871887, 2015). "TCF12 directly interacts with TWIST1, mutated in Saethre-Chotzen syndrome (OMIM#601622), which features complex craniosynostosys with variable degrees of intellectual disability, including ASD traits." (PMID 27621700, 2016). "We report here on a 72‐year‐old patient presenting with intellectual disability, dysmorphism, and a TCF12 microdeletion detected by array‐comparative genomic hybridization." (PMID 25871887, 2015). "The inclusion of TCF12 in gene panels for the investigation of intellectual disability should be considered." (PMID 25871887, 2015).
leukemia (6 papers, 2013 to 2025). A malignant (clonal) hematologic disorder, involving hematopoietic stem cells and characterized by the presence of primitive or atypical myeloid or lymphoid cells in the bone marrow and the blood. "More importantly, the breakdown in TCF12–IGH::DUX4 cooperation impaired IGH::DUX4‐driven leukaemia cell survival, caused sensitivity to the chemotherapy." (PMID 38115701, 2023). "It is also notable that Lck-TAL1 promotes leukemia in a dose-dependent manner that is augmented by deletion of the E proteins encoded by Heb/Tcf12 indicating that E protein dose is a major determinant of leukemogenesis in this model." (PMID 35514954, 2022). "Indeed, based on the results of cell proliferation, apoptosis, and drug sensitivity experiments, it was clear that the loss of TCF12 could result in impaired leukaemia cell survival and resistance to chemo drug such as vincristine." (PMID 38115701, 2023). "In order to characterise this further, we also conducted the TCF12 rescue experiments, in which the WT TCF12 and mutant (D393A/E394A) were re‐expressed in the leukaemia NALM‐6TCF12−/− cells." (PMID 38115701, 2023). "The next closely related motifs came from TFs PU.1 (a crucial factor in both hematopoiesis and leukaemia) and Tcf12, bearing 21.23% and 29.78% similarities to IGH::DUX4, respectively." (PMID 38115701, 2023). "Supportively, when TCF12 expression was inhibited in these leukaemia cells, the IGH::DUX4‐driven transcription was significantly reduced." (PMID 38115701, 2023). "Upon re‐expression of TCF12 in the leukaemia cells, the IC50 value was recovered to a WT NALM‐6 level (5.1 nM)." (PMID 38115701, 2023). "Supportively, knockdown and knockout of TCF12 significantly reduced expression of IGH::DUX4‐driven target genes in leukaemia REH (a precursor B‐cell leukaemia cell line) and NALM‐6 cells (a precursor B‐cell leukaemia cell line)." (PMID 38115701, 2023). "In IGH::DUX4 leukaemia, the oncogenic driver might recruit TCF12 via a positively self‐regulatory feedback loop to beef up its oncogenic transcription activity." (PMID 38115701, 2023). "Finally, to validate the synergistic role of TCF12 in promoting IGH::DUX4 leukaemia, cell proliferation, apoptosis and drug sensitivity experiments were performed." (PMID 38115701, 2023). "The dysregulated genes were identified in the two‐dimensional (2D) representation of the gene expression profile following t‐distributed stochastic neighbour embedding dimensionality reduction, wherein patients with DUX4‐fused leukaemia exhibited pronounced upregulation of TCF12." (PMID 38115701, 2023). "Interestingly, TCF12 is also expressed in lymphoid malignancies, suggesting a role in B- and T-cell-derived leukemia." (PMID 34021250, 2021). "Based on these results observed in B‐ALL patients, leukaemia cells and structural simulation, an IGH::DUX4 cofactor TCF12 was proposed." (PMID 38115701, 2023). "The leukaemia cell line NALM‐6 can stably express IGH::DUX4 endogenously, and hence provide us with a perfect opportunity to monitor the effect of TCF12 depletion on IGH::DUX4 in leukaemia cells." (PMID 38115701, 2023). "The expressions of CLEC12Aalt and CLEC12A were consistently increased in leukaemia cells that harbored both IGH::DUX4 and TCF12." (PMID 38115701, 2023). "Firstly, the available leukaemia cells REH and NALM‐6 were used for TCF12 overexpression and knockdown analysis." (PMID 38115701, 2023). "This discovery, along with transcriptomic data analysis from 1223 patients, indicated that TCF12 might act as a cofactor in the abnormal transcriptional function and disease development of IGH::DUX4 leukaemia." (PMID 38115701, 2023). "Altogether, these results helped to define a previously unrecognised TCF12‐mediated positive self‐feedback regulatory mechanism in IGH::DUX4 leukaemia, which holds the potential to function as a pivotal drug target for the management of this particular form of leukaemia." (PMID 38115701, 2023).
leukemia (continued). "In this leukaemia subtype, TCF12 could act as a cofactor in regulating the transcriptional mechanism of IGH::DUX4 via a positive self‐feedback regulatory interplay between IGH::DUX4 and TCF12." (PMID 38115701, 2023).
prostate carcinoma (5 papers, 2017 to 2024). A carcinoma that arises from epithelial cells of the prostate gland. "For instance, MYF5 and MYOD as transcription factors are mutually-exclusively expressed, and each is required for sustained tumor growth; TCF12 is a poor prognostic factor of ovarian cancer and prostate cancer." (PMID 33178820, 2020). "EMX2OS is a key metabolism-related enhancer RNA in KIRC with a favorable impact on survival and EMX2OS is regulated by TCF12 transcription and co-regulates the proliferation, migration and invasion of prostate cancer cells with FUS protein by activating cGMP-PKG pathway." (PMID 33517850, 2021). "QRT-PCR showed a trend toward prostate cancer cell lines having higher HIF-1a and TCF12 mRNA expression than the normal prostate cell line (p < 0.05)." (PMID 29069829, 2017). "Although the transcription factors of stemness genes have similar expressions, they have different contributions between normal and prostate cancer tissues; and particular transcription factors enhance the stemness of prostate cancer, such as PUM1, CLOCK, SP1, TCF12, and so on." (PMID 33985534, 2021). "The role of TCF12 in prostate cancer has not been reported yet." (PMID 29069829, 2017).
anaplastic oligodendroglioma (4 papers, 2015 to 2023). A WHO grade III oligodendroglioma with focal or diffuse malignant morphologic features (prominent nuclear pleomorphism, mitoses, and increased cellularity). "Interestingly, it has been shown that TCF12 is mutated in a fraction of human anaplastic oligodendrogliomas." (PMID 37046694, 2023). "Although TCF12 mutations were not previously reported in DIPG, they were shown in anaplastic oligodendroglioma to correlate with more aggressive tumor types." (PMID 32680567, 2020).